PTMAP5 (prothymosin alpha pseudogene 5)
Gene: Transcribed processed pseudogene on chromosome 13 (81,690,068 to 81,690,400, forward strand). Ensembl gene ENSG00000214182.
Diseases named in the same sentence as PTMAP5 in open-access papers:
PTMAP5 is named in the same sentence as 1 disease in open-access papers, as found by Europe PMC text mining. Sharing a sentence is not in itself a finding about the gene and the disease.
PTMAP5 shares sentences with these, for which no sentence is quoted: lung adenocarcinoma (1 paper).